ATM (ATM serine/threonine kinase)
Diseases named in the same sentence as ATM in open-access papers (continued):
Sharing a sentence is not in itself a finding about the gene and the disease.
lung carcinoma (continued). "To understand the interplay of ATM-L2307F and the somatic mutation profiles, we utilized the germline and matched tumor data for 2127 lung cancer patients of European ancestry in an additional, independent MSK-IMPACT dataset." (PMID 32393777, 2020). "ATM-L2307F was found to have high prevalence in Ashkenazi Jews and the association with lung cancer was stronger in a population from Israel." (PMID 32393777, 2020). "It remains to be tested if variants in other populations also contribute to lung cancer susceptibility, or if L2307F co-occurring with other clearly pathogenic ATM mutations increases lung cancer risk beyond that experienced by heterozygotes." (PMID 32393777, 2020). "Here the authors looked at rare variants in 39,146 individuals and find novel germline mutations associated with risk, as well as implicating ATM and a new candidate gene for lung cancer risk." (PMID 32393777, 2020). "A previous study showed that ATM rs189037 is associated with radiation- induced pneumonia in lung cancer patients, but, its role in survival outcomes of NSCLC patients has not been reported." (PMID 32329754, 2020). "In this study, we investigated the effects of Ataxia Telangiectasia Mutated (ATM) on lung cancer metastasis." (PMID 30961670, 2019). "Recently, an ATM germline polymorphism has been significantly associated with lung cancer susceptibility." (PMID 30172261, 2018). "Our results support the experimental study findings on the role of ATM SNPs in development of lung cancer especially in individuals with homozygous variant alleles." (PMID 28642860, 2017). "A large proportion of these mutations were found in lung cancers, which exhibited the highest rate of somatic ATM mutations of all tumours analyzed." (PMID 28418844, 2017). "A recent case–control study in Taiwanese population (358 cases and 716 controls) examined the association of ATM polymorphisms, including ATMrs227060 and ATMrs228589 with lung cancer." (PMID 28642860, 2017). "In the current study, we investigated the association of these two ATM SNPs with lung cancer in a Chinese population." (PMID 28642860, 2017). "We found that ATM rs189037 polymorphism A allele was associated with an increased risk of lung cancer (AA versus AG/GG, OR = 1.16, 95% CI = 1.03–1.32; AA versus GG, OR = 1.21, 95% CI = 1.04–1.39; A versus G, OR = 1.09, 95% CI = 1.02–1.17)." (PMID 29246212, 2017). "One study suggested that ATM mutated lung carcinomas are highly susceptible to MEK1/2 inhibitor treatment." (PMID 28804793, 2017). "The results indicate that the ATM rs189037, rs664677 and rs664143 gene polymorphisms are risk factors for lung cancer, while the ATM rs189037 variant was significantly associated with RP risk." (PMID 29246212, 2017). "All three existing studies including the current study that investigated the association of the ATM SNPs (rs227060 and rs228589) and lung cancer had relatively small sample size." (PMID 28642860, 2017).
lung carcinoma (continued). "Previous studies have suggested that the ATM gene plays a critical role in DNA damage repair and thereby affects the risk of lung cancer and RP." (PMID 29246212, 2017). "We also explored potential interaction between the ATM SNPs and smoking, alcohol intake, and tea drinking behaviors in association with lung cancer." (PMID 28642860, 2017). "In conclusion, in this meta-analysis, we showed that the ATM rs189037 polymorphism is significantly associated with lung cancer and the risk of RP after radiotherapy." (PMID 29246212, 2017). "Among these, 10 studies included 4731 cases and 5142 controls, evaluated four single nucleotide polymorphisms (SNPs), and were focused on the association between ATM gene polymorphisms and susceptibility to lung cancer." (PMID 29246212, 2017). "Potential gene–gene and gene–environment interactions of ATM gene polymorphisms in association with lung cancer." (PMID 28642860, 2017). "For the ATM rs189037polymorphism, 3043 cases and 3430 controls from five case- control studies on lung cancer susceptibility were included in the present meta-analysis." (PMID 29246212, 2017). "Lung cancer cells resistant to MEK inhibition become highly sensitive upon loss of ATM both in vitro and in vivo." (PMID 27922010, 2016). "ATM protein is lost in a number of cancer cell lines and ATR kinase inhibitors synergize with cisplatin to resolve xenograft models of ATM-deficient lung cancer." (PMID 27259260, 2016). "ATM SNPs have been associated with increased risk of breast, prostate, leukaemia, colon and lung cancer." (PMID 27557076, 2016). "Despite that ataxia-telangiectasia mutated (ATM) is involved in IL-6 promoted lung cancer chemotherapeutic resistance and metastasis, the exact role of ATM in tumor necrosis factor-alpha (TNF-α) increasing tumor migration is still elusive." (PMID 27556690, 2016). "We show that ATM mutation in lung cancer cells results in a strong sensitization to drugs targeting MEK, including the FDA-approved drug trametinib." (PMID 27922010, 2016). "The majority of lung cancer mutations, such as ATM (ataxia–telangiectasia mutated) loss-of-function mutations, which are found in 5–10% of patients, are not actionable with small-molecule inhibitors." (PMID 27922010, 2016). "Together our results reveal that a heterogeneous panel of lung cancer cells carrying ATM mutations is associated with high sensitivity to MEK inhibition." (PMID 27922010, 2016). "The results of our ATM phosphorylation studies also revealed that the presence of caffeine caused an increase of cisplatin-induced ATM phosphorylation at Ser1981 in these lung cancer cells." (PMID 25937999, 2015). "The striking conclusion from these analyses is that while ATM is mutated in a subset of lung cancers, ATR is amplified in subset of lung cancers." (PMID 26438152, 2015). "Epidemiological studies have demonstrated that ATM gene polymorphisms are related to cancer risk including lung cancer, breast cancer, glioma and pancreatic cancer." (PMID 25541996, 2014). "S1 Table presents the genotype distribution of ATM SNP rs189037 and its associations with lung cancer risk in this Chinese Han population." (PMID 25541996, 2014). "In conclusion, our research showed that ATM rs189037 single nucleotide polymorphism was associated with lung cancer risk in Chinese Han population." (PMID 25541996, 2014). "As several previous studies significantly support the association between ATM signal pathway and lung cancer susceptibility, we did a further research concentrating on ATM gene polymorphism and its association with lung cancer risk." (PMID 25541996, 2014). "Accumulated evidence has indicated that ataxia-telangiectasia mutated (ATM) gene polymorphisms are closely related to lung cancer." (PMID 25541996, 2014).
lung carcinoma (continued). "Compared with the homozygous wild type (GG) in our Chinese people, we observed participants with the homozygous variant genotype (AA) of ATM SNP rs189037 contributed to increased lung cancer risk (adjusted OR: 1.56, 95% CI: 1.18–2.08)." (PMID 25541996, 2014). "In the present study, we selected and genotyped rs189037 in the promoter region of ATM gene located on 11q22–23, there is a statistically significant association between rs189037 and lung cancer risk in this Chinese Han population." (PMID 25541996, 2014). "For example, mutations in ataxia telangiectasia-mutated (ATM) have been associated with increased risk of development of lung cancer." (PMID 26316936, 2012). "Approximately 40% of NSCLCs have loss of ATM protein expression, identifying a significant proportion of lung cancer patients whose tumors may be exquisitely sensitized to ATR kinase inhibition." (PMID 41206673, 2025). "Indeed, in BRCA1- or ATM-mutated breast, ovarian and lung cancer lines, low EME1 levels associated with decreased Olaparib sensitivity, which was not the case in BRCA2-mutated or unaltered cells." (PMID 39994444, 2025). "Furthermore, there is increasing evidence showing that heterozygous mutations in the ATM gene are associated with an increased risk of developing a wide spectrum of malignancies, including breast, stomach, and lung cancers." (PMID 38882696, 2024). "Another study found that ATM inhibition or loss of FANCD2 conferred a reduction in HRR and RAD51 foci formation in lung cancer, which is consistent with our finding that complete ATM loss in NGP cells impaired HRR through the downregulation of FANCD2 and RAD51 expression." (PMID 37020276, 2023). "In addition, germline mutations of ATM are associated with gastric cancer as well as lung carcinoma." (PMID 35347810, 2022). "For instance, ATM deficient or constitutive Myc proto-oncogen expressing mice lacking caspase-2 develop lymphoma with significantly higher incidence and rate, whereas Kras expressing mice develop lung cancer with increased incidence when caspase-2 is depleted." (PMID 35444189, 2022). "It has been reported that mutations in ATM are found in approximately 10% of lung cancers." (PMID 36243681, 2022). "Indeed, a meta-analysis has shown that in the ATM gene, the rs189037, the rs664677 and the rs664143 polymorphisms are associated with susceptibility to lung cancer, while the rs189037 variant is also associated with radiation-induced pneumonitis risk." (PMID 35740268, 2022). "Notably, ATM gene somatic mutations have been illustrated to play a role in the pathophysiology of lung cancer." (PMID 33802234, 2021). "Similarly, ATM is mutated in ~20% of colorectal and uterine cancers and approximately 10% of prostate and lung cancers." (PMID 32183301, 2020). "Similarly, recent publications showed the efficacy of using Trametinib (MEK inhibitor) in lung cancer cells with ATM mutations." (PMID 32645997, 2020). "Furthermore, we corroborated the in vitro efficacy of AZD6738/olaparib observed in ATM-KO FaDu cells using ATM-deficient lung carcinoma cell lines, and in vivo xenograft and PDX ATM-deficient models." (PMID 32444694, 2020). "However, the associations that we found in our study contribute to the understanding of the potential role of ATM gene polymorphisms in the development of lung cancer and justify the need to pursue validation in larger studies." (PMID 28642860, 2017). "In particular, the association of ATM haplotypes and ATM SNPs with lung cancer among risk factor strata may have been affected by the smaller subgroup samples and these results should be interpreted cautiously." (PMID 28642860, 2017).
lung carcinoma (continued). "Previous studies have shown that several ATM gene polymorphisms (e.g., rs664143, rs664677, rs189037, and rs609429) may be associated with susceptibility to lung cancer, and that others (e.g., rs189037) may be associated with RP risk." (PMID 29246212, 2017). "Therefore, we conducted this comprehensive meta-analysis to evaluate the association between ATM gene polymorphisms and both susceptibility to lung cancer and the risk of RP in lung cancer patients treated with radiotherapy." (PMID 29246212, 2017). "This study indicates that ATM gene variants might be associated with development of lung cancer in Chinese population." (PMID 28642860, 2017). "In conclusion, our findings demonstrate that ATM, which could be activated by lung cancer-associated TNF-α, up-regulate MMP-13 expression and thereby augment tumor metastasis." (PMID 27556690, 2016). "Thus, our findings suggest that including ATM mutational status in lung cancer as a mechanistic biomarker for MEK inhibitors can improve patient stratification, potentially extending the applicability of these drugs beyond RAS and BRAF mutant tumours." (PMID 27922010, 2016). "ATM loss also enhances the sensitivity of KRAS- or BRAF-mutant lung cancer cells to MEK inhibition." (PMID 27922010, 2016). "To investigate whether the ATM-MEK gene–drug association also occurs in lung cancer cells harbouring ATM mutations, we assembled a set of nine ATM mutant and seven wild-type control lung cancer cell lines." (PMID 27922010, 2016). "This seems at odds with the observation that many of the ATM mutations in lung cancer are heterozygous and may thus only partially impair ATM." (PMID 27922010, 2016). "Furthermore, cisplatin and ATR kinase inhibitors synergize to kill ATM-deficient lung cancer cells in vitro and to resolve ATM-deficient xenografts in vivo." (PMID 27259260, 2016). "Remarkably, the combination of cisplatin and AZD6738 resolves ATM-deficient lung cancer xenografts." (PMID 26517239, 2015). "As cigarette smoking might modulate the risk of lung cancer, in turn it could be a confounder in the association between ATM rs189037 and lung cancer risk." (PMID 24819391, 2014). "We aimed to explore the prognostic value of rs189037 (G>A), one of ATM single nucleotide polymorphisms (SNPs), and detect whether it involves in the risk of lung cancer in Chinese Han people." (PMID 25541996, 2014). "Previous studies of ATM rs189037 have included cigarette smokers as cases and controls that made it difficult to judge whether this polymorphism were associated with lung cancer or tobacco use." (PMID 24819391, 2014). "Accumulated evidence has indicated that ATM gene polymorphisms are closely related to lung cancer." (PMID 25541996, 2014). "For example, germline variants in BRCA2 and ATM may cause increased risk for lung cancer and sarcoma, two tumor types in our study that revealed a significant number of tumor (and germline) variants in hereditary cancer risk genes not typically associated with these tumor types." (PMID 36261688, 2023). "This may explain the similar associations of the two ATM SNPs with lung cancer in our study." (PMID 28642860, 2017). "Acquired ATM loss may be exploited for clinical benefit as pharmacologic ATR kinase inhibitors including VE-821, VE-822/VX970 and AZD6738 synergize with cisplatin to kill ATM-deficient cancer cells in vitro and to resolve xenograft models of ATM-deficient lung cancer in vivo." (PMID 27259260, 2016). "Therefore, ATM might be a promising target for prevention of inflammation-associated lung cancer metastasis." (PMID 27556690, 2016). "Thus, ATM mutational status in lung cancer is a mechanistic biomarker for MEK inhibitor response, which may improve patient stratification and extend the applicability of these drugs beyond RAS and BRAF mutant tumours." (PMID 27922010, 2016).
lung carcinoma (continued). "We did this case-control study to dig out the association between ATM single nucleotide polymorphism (SNP) rs189037 and lung cancer risk in a Chinese population, which supported that genetic factor played an important role in individual lung cancer susceptibility." (PMID 25541996, 2014). "The same analysis reported the common features of the associated lung cancer, including the adenocarcinoma pathology and at least one driver mutation in nearly half of the cases, including KRAS, EGFR, ALK, BRAF, and ATM." (PMID 41476748, 2025). "Li identified ATM and KEAP1 as new targets in lung cancer, and KEAP1 deficiency sensitized lung tumors to ATM inhibition." (PMID 38347129, 2024). "In lung cancer, suppression of ATM enhanced the sensitivity of DDP and EMT progression via JAK/STAT3/PD-L1 pathway." (PMID 38993556, 2024). "PURPOSE: To explore the relationship between ATM, ATR and CAT polymorphisms and prognosis of lung cancer patients received platinum-based chemotherapy." (PMID 36969849, 2023). "Herein, we investigated the association of potentially functional SNPs in ATM, ATR and CAT with platinum-based chemotherapy outcome of lung cancer patients." (PMID 36969849, 2023). "IL-24 Inhibits lung cancer growth by suppressing glioma-associated oncogene homolog 1 (GLI1), associated with marked suppression of the ATM-mediated DNA damage response pathway, which results in increased DNA damage." (PMID 37444474, 2023). "Authentically, a viable lung cancer-targeted therapeutic approach is offered by the combinatorial regimen, which in fact inhibits the ATM pathway to improve the tumor suppressive potential of VP-16." (PMID 36650267, 2023). "PKA has been recognized as a potent negative regulator of ATM activation through PKA-dependent activation of PP2A in lung cancer cells." (PMID 37444474, 2023). "ATM knockout models of pancreatic, prostate, and lung cancers have been shown to lead to enhanced efficacy with PARP and/or ATR inhibition." (PMID 37627223, 2023). "Herein, we mechanistically and functionally demonstrate the therapeutic potential of VP-16 in combination with ATM inhibitors for the eradication of lung cancer cells." (PMID 36650267, 2023). "CAMP signaling increases histone deacetylase 8 (HDAC8s) expression through the Epac–Rap1–Akt pathway leading to augmenting cisplatin-induced apoptosis and inhibits radiation-induced ATM phosphorylation promoting apoptosis in lung cancer." (PMID 35419410, 2022). "Other targets, such as Ataxia Telangiectasia Mutated (ATM), have been reported to upregulate PD-L1 expression via the JAK1, 2/STAT3 pathway, mediating the cisplatin-resistance in lung cancer cells." (PMID 36559280, 2022). "Uptake of [18F]1 was assessed in vitro in H1299 lung cancer cells stably transfected with shRNA to reduce expression of ATM." (PMID 35962885, 2022).